GLI1 (GLI family zinc finger 1)
Diseases named in the same sentence as GLI1 in open-access papers (continued):
Sharing a sentence is not in itself a finding about the gene and the disease.
chronic lymphocytic leukemia (3 papers, 2019 to 2023). "The glioma associated oncogene-1 (GLI1), a downstream effector of the embryonic Hedgehog pathway, was detected in chronic lymphocytic leukemia (CLL), but not normal adult cells." (PMID 33747356, 2021). "STAT3 not only frequently forms transcriptional complexes with GLI1 and GLI2, binding to their zinc finger domains to promote transcription, but it can also directly enhance the expression of GLI1 in chronic lymphocytic leukemia cells." (PMID 37919751, 2023).
colon adenocarcinoma (3 papers, 2009 to 2024). "Furthermore increased expression of SHH mRNA in human colonic adenocarcinomas is known to correlate with downstream increased expression of GLI1 leading to promotion of cell proliferation." (PMID 19706168, 2009).
cyst (3 papers, 2016 to 2022). A sac-like closed membranous structure that may be empty or contain fluid or amorphous material. "While normal ciliary structure does not mean normal function, the ectopic Gli1 expression in Six2creFrs2αKO was most notable in the expanding interstitium and was rarely observed in cyst lining cells." (PMID 27853247, 2016). "In P7 controls and mutants, we observed similar medullary Gli1 staining; however, mutants had ectopic Gli1 expression in the renal cortical interstitium, usually adjacent to cysts, but almost never in cyst lining cells." (PMID 27853247, 2016). "However, in the case of OKCs, it is believed that the sum of this cytoplasmic SMO/GLI-1 correlation along with the strong cytoplasmic and nuclear expression of GLI-1 may contribute to the high growth potential of this cyst." (PMID 36287504, 2022). "Thus, it appears that ectopic mutant Shh protein in non-dilated proximal tubules in early postnatal kidneys likely triggers the ectopic Gli1 expression in the mutant interstitium (and that the cyst lining cells are not driving the augmented hedgehog response)." (PMID 27853247, 2016).
Down syndrome (3 papers, 2015 to 2025). "A study showed a relation between a decreased expression of the HH target gene GLI1 and the appearance of VSDs in Down syndrome patients, indicating that reduced HH signalling provokes VSDs in these patients." (PMID 29615572, 2017). "Furthermore, an association between a reduced expression of the HH target gene GLI1 and the occurrence of VSDs was reported in Down syndrome patients." (PMID 29615572, 2017).
Ductal carcinomas in situ (3 papers, 2009 to 2025). "The %GLI1 nuclear translocation correlated with invasiveness, and there was a serial increase in %GLI1 translocation from ductal carcinoma in situ to invasive ductal carcinoma." (PMID 31394751, 2019). "Ductal carcinomas in situ and invasive breast tumours are both characterised by abundant nuclear GLI1 expression." (PMID 19706168, 2009).
E. coli infection (3 papers, 2018 to 2025). "Employing an in vivo murine model with Gli1 deletion, we further verified the role of SHH–Gli1 signaling in mediating primitive hematopoietic precursor cell activation during the granulopoietic response to systemic E. coli infection." (PMID 29535725, 2018). "Transcriptional activation is involved in the increase in Gli1 expression by hematopoietic precursor cells in response to E. coli infection." (PMID 29535725, 2018). "Gli1 gene deletion inhibited the increase in granulocytes in the blood stream following systemic E. coli infection." (PMID 29535725, 2018). "In response to systemic E. coli infection, marrow hematopoietic cells significantly increased Gli1 expression in our current study." (PMID 29535725, 2018). "The enhancement of Gli1 expression was also detected in marrow lin+ cells during systemic E. coli infection in this study." (PMID 29535725, 2018). "Whether the molecular phenotype of prostate recruited myeloid cells (expression of Gli1, Lyz2, S100a4) and other markers changes over time, especially after resolution of E. coli infection, was not examined in this study." (PMID 39748675, 2025). "E. coli infection increased the proportion of RFP+ cells that co-express Ki67 in mice of Lyz2+ and Gli1+ cell lineages, but not in mice of Cd2+ and S100a4+ cell lineages." (PMID 39748675, 2025).
Gastric Metaplasia (3 papers, 2013 to 2023). Intestinal metaplasia of the gastric mucosa is an intermediate precancerous gastric lesion in the gastric cancer cascade from chronic gastritis and atrophy to dysplasia and adenocarcinoma. "Similar effects were found in transgenic GLI1-deficient mice infected with H. felis, which were largely resistant to the development of gastric metaplasia and infiltration by inflammatory cells." (PMID 28427431, 2017). "Therefore to test whether Hh signaling is required for gastric transformation, we infected wild type C57BL/6 (WT) and Gli1-deficient mice with Helicobacter felis (H. felis) to generate a robust inflammatory response (chronic gastritis) and gastric metaplasia." (PMID 23520544, 2013). "Although Gli1 deletion demonstrated that a component of the Hh signaling pathway is necessary for inflammation and gastric metaplasia, we examined whether ectopic expression of the Shh ligand was sufficient to induce these lesions." (PMID 23520544, 2013).
invasive breast carcinoma (3 papers, 2009 to 2024). A carcinoma that infiltrates the breast parenchyma. "In breast invasive carcinoma, GLI1 expression was significantly higher in normal tissue compared with tumor tissue." (PMID 39483334, 2024). "Our analyses confirm that GLI1 serves as a prognostic biomarker in breast invasive carcinoma, correlating with pathological stages and survival outcomes in this disease." (PMID 39483334, 2024). "With the aim of comprehensively investigating the significance of GLI1 in breast invasive carcinoma (BRCA), this study was designed to address three key aspects." (PMID 39483334, 2024). "However, the expression and specific roles of GLI1 in breast invasive carcinoma have been scarcely explored." (PMID 39483334, 2024). "High expression of GLI1 positively correlated with the abundance of infiltrating immune cells, such as DCs and CD4+ T cells, suggesting that GLI1 may partially regulate the recruitment of immune cells in the TMIE of breast invasive carcinoma." (PMID 39483334, 2024). "Therefore, our study aims to comprehensively investigate the roles of GLI1 in breast invasive carcinoma." (PMID 39483334, 2024).
invasive ductal carcinoma (3 papers, 2016 to 2019). "Histopathological studies of ductal carcinomas in situ (DCIS) and invasive ductal carcinomas (IDC) support a role of GLI1 expression in acquisition of the invasive phenotype, since IDC samples show an increased % of cells with nuclear GLI1 staining." (PMID 31027259, 2019).
liver disease (3 papers, 2017 to 2022). "Overall, the genetic evidence of EpCAM+Gli1+ cells in liver repair provides new insights into the cellular and molecular mechanisms of liver disease and regeneration." (PMID 36316325, 2022).
meningioma (3 papers, 2023). A generally slow growing tumor attached to the dura mater. "As the GLI1 transcription factor is a primary effector of the Hh signaling pathway, amplification of this gene most likely underlies Hh activation in this meningioma." (PMID 37805627, 2023). "Here, we provide evidence that NF2-deficient meningiomas express significantly higher levels of widely recognized oncogenes BCL2 and GLI1 compared to meningiomas with missense TRAF7 mutations." (PMID 36937440, 2023). "The analysis revealed that meningiomas with NF2 gene inactivation expressed higher levels of BCL2 and GLI1 compared with tumors harboring TRAF7 missense mutations." (PMID 36937440, 2023). "Taken together, these results suggest that dysregulation of the Hedgehog signaling pathway and subsequent increased expression of GLI1 and BCL2 may play a role in the development of meningioma as is the case in other cancers." (PMID 36937440, 2023). "Taken together with the high expression of BCL2 and GLI1, these results suggest that activation of Sonic Hedgehog pathway may contribute to NF2 meningioma development." (PMID 36937440, 2023).
multiple sclerosis (3 papers, 2018 to 2022). A progressive autoimmune disorder affecting the central nervous system resulting in demyelination. "Although a more thorough investigation of the joint impact of these mutations on multiple sclerosis is warranted, GLI-1 is a therapeutic target of much interest in cancer, including through its interaction with SUFU, suggesting a starting point for further research." (PMID 35501860, 2022). "Remarkably, the small molecule GANT61 successfully inhibits Gli1 and improves remyelination in an experimental animal model for multiple sclerosis." (PMID 30279648, 2018). "Interestingly, the kinetics of Gli1 transcription determined in the EAE model reminds the regulation of Gli1 expression determined in the brain from multiple sclerosis patients as shown by the upregulation of Gli1 in active lesions and its decrease in chronic active and inactive lesions." (PMID 30237763, 2018).
Myocardial fibrosis (3 papers, 2022 to 2025). "After administering the Gli‐1 inhibitor GANT‐61, the degree of myocardial fibrosis was reduced, and Gli‐1 expression was also inhibited." (PMID 36102251, 2022). "Gli‐1 inhibitors are also clinically promising treatments for inhibiting CKD‐induced myocardial fibrosis." (PMID 36102251, 2022). "Previous studies have found that miR-325 alleviates myocardial fibrosis after myocardial infarction by downregulating GLI1." (PMID 35136419, 2022). "Studies have found that miR-325 alleviated myocardial fibrosis after myocardial infarction by downregulating GLI1." (PMID 35136419, 2022). "Therefore, we propose that CKD causes myocardial fibrosis and that the degree of myocardial fibrosis caused by CKD is reduced after the use of the Gli‐1 inhibitor GANT‐61, which targets the hedgehog signaling pathway." (PMID 36102251, 2022). "The CKD model was treated with the glioma 1 (Gli‐1) inhibitor GANT‐61, and myocardial fibrosis and serum intact fibroblast growth factor 23 levels were assessed 16 weeks after nephrectomy." (PMID 36102251, 2022). "Using GANT‐61, an inhibitor of the Shh signaling pathway component Gli‐1, we observed an attenuation of CKD‐induced myocardial fibrosis." (PMID 36102251, 2022). "The degree of myocardial fibrosis in SD rats with CKD was attenuated in the presence of GANT‐61, a Gli‐1 inhibitor of the Hedgehog signaling pathway." (PMID 36102251, 2022). "However, the Gli‐1 inhibitor we studied unfortunately did not attenuate hypertension while inhibiting myocardial fibrosis in the CKD model." (PMID 36102251, 2022).
Obesity (3 papers, 2019 to 2024). Accumulation of substantial excess body fat. "For instance, obesity downregulates SHH signaling, including the expression of GLI1, GLI2, and GLI3." (PMID 31316554, 2019).
scleroderma (3 papers, 2020 to 2023). Scleroderma is a rare autoimmune connective tissue disorder characterized by abnormal hardening of the skin and, sometimes, other organs. "Hedgehog signaling and accumulation of Gli1 and Gli2 have been reported to have a role in scleroderma." (PMID 37700377, 2023). "The induction of the fibrotic phenotype of scleroderma is mediated through GLI1/GLI2 (the effector molecules of the Hedgehog pathway) to promote tissue fibrosis." (PMID 35008794, 2021). "GLI1/GLI2 (the effector molecules of the Hedgehog pathway) promote tissue fibrosis by inducing the fibrotic phenotype of scleroderma." (PMID 35008794, 2021). "We additionally demonstrate that the promoters of the hedgehog-associated genes GLI1 and PTCH1 are more readily accessible in scleroderma fibroblasts." (PMID 32814713, 2020). "We then evaluated how primary dermal fibroblasts from scleroderma and normal skin regulate promoter accessibility of JUN and the hedgehog-associated genes GLI1 and PTCH1 through assay of transposase accessible chromatin sequencing (ATAC-Seq) studies." (PMID 32814713, 2020). "In accordance with our hypothesis, promoter accessibilities of JUN, GLI1, and PTCH were increased in scleroderma compared with normal skin." (PMID 32814713, 2020).
skin basal cell carcinoma (3 papers, 2014 to 2020). The most frequently seen skin cancer. "While GLI1 is itself a GLI1 regulatory target, in basal cell skin carcinoma cells, activation of GLI2 by GLI1 is indirect, and perhaps context dependent." (PMID 25252859, 2014).
Ureteral obstruction (3 papers, 2024 to 2025). Obstruction of the flow of urine through the ureter. "In unilateral ureteral obstruction (UUO) models, rhein reduces the expression of SHH, Gli1, and Snail, significantly improving renal interstitial fibrosis by regulating the SHH-Gli1-Snail signaling pathway." (PMID 39770507, 2024).
acute T-cell lymphoblastic leukemia (2 papers, 2018). "HH-GLI pathway mutation analysis in T-cell acute lymphoblastic leukemia discovered the presence of two rare somatic missense substitutions—GLI1:c.C1613T (p.S538F) and GLI3:c.G2179A (p.G727R)." (PMID 30158435, 2018). "A relationship between GLI1 and JAK3 was identified in acute T-cell lymphoblastic leukemia, where their expression levels showed a positive correlation." (PMID 29789566, 2018).
ameloblastoma (2 papers, 2013 to 2022). The most common odontogenic tumor, arising from the epithelial component of the embryonic tooth and usually affecting the molar-ramus region of the mandible or maxilla. "We detected expression of SHH, patched, GLI1, GLI2 and GLI3 in the ameloblastoma specimens and AM-1 cells." (PMID 23835807, 2013). "In the present study, we examined the expression of SHH, PTCH, GLI1, GLI2, and GLI3 in ameloblastoma and investigated their functions using an ameloblastoma cell line." (PMID 23835807, 2013). "In ameloblastoma, immunoreactivity for SHH, PTCH, GLI1, GLI2 and GLI3 was seen in almost all tumor cells, but not in the stromal cells." (PMID 23835807, 2013).
anaplastic large cell lymphoma (2 papers, 2009 to 2019). Anaplastic large cell lymphoma (ALCL) is a rare and aggressive peripheral T-cell non-Hodgkin lymphoma, belonging to the group of CD30-positive lymphoproliferative disorders, which affects lymph nodes and extranodal sites. "Singh and colleagues also reported that PI3K/AKT contributes to activation of the HH/GLI1 signaling pathway in ALK-positive anaplastic large cell lymphoma (ALCL), but not in ALK-negative ALCL." (PMID 19575820, 2009).
asthma (2 papers, 2013 to 2024). "There are two FDA-approved drugs that target GLI1/2; however, ciclesonide was initially approved for treatment of asthma, and its mechanism of inhibiting GLI1/2/SOX2 expression is unknown." (PMID 38920995, 2024).
atypical teratoid rhabdoid tumor (2 papers, 2020 to 2025). Atypical teratoid rhabdoid tumor (ATRT) is a highly malignant central nervous system (CNS) rhabdoid tumor (RT) found almost exclusively in children. "An atypical teratoid rhabdoid tumor (ATRT) is caused by loss of the INI1 subunit and has been shown to be linked to aberrant activation of signaling pathways dependent on two TFs–MYC or GLI1." (PMID 40065228, 2025).
bone tumors (2 papers, 2019 to 2024). "(F) Western blot showed an increase in Gli1 in bone tumor tissues isolated from Prrx1-CreERT; Ptch1f/f mice compared to normal periosteal cells." (PMID 31482846, 2019). "Immunohistochemical staining of 24 human cartilage/bone tumors revealed that β–Catenin levels were increased in most of the tumor samples compared with normal tissues, which was correlated with increased levels of Gli1." (PMID 31482846, 2019). "(H) Relationship between the protein levels of Gli1 and β-Catenin in human cartilage/bone tumors." (PMID 31482846, 2019).
Burkitt lymphoma (2 papers, 2018 to 2019). A rare form of malignant mature B-cell non-Hodgkin lymphoma. "c-MYC, one of the most frequently deregulated transcription factors in cancer, has been found to regulate GLI1 expression, thus supporting an antiapoptotic role of GLI1 in Burkitt lymphoma." (PMID 29695137, 2018).
ciliopathies (2 papers, 2020 to 2022). "Furthermore, protein pathways associated with autophagy, apoptosis, cilium assembly and Gli1 protein were upregulated in both ciliopathies." (PMID 36553637, 2022). "However, we also described a new group of patients (group 4: GLI1+/IFT20+) expressing/re-expressing the primary cilium in a ciliopathy context." (PMID 32194829, 2020).
colorectal adenocarcinoma (2 papers, 2014 to 2025). The most common type of colorectal carcinoma. "The results demonstrated that p,p′-DDE exposure promoted colorectal adenocarcinoma cell proliferation through activated Wnt/β-catenin and Hedgehog/Gli1 signalings, which were mediated by oxidative stress." (PMID 25386960, 2014). "From a clinical perspective, given the uncertain malignant potential of GLI1 fusion-associated tumours, and in the context of her ongoing adjuvant chemotherapy (8 cycles of XELOX for 6 months) for colorectal adenocarcinoma, surgical management of the pleural lesion was deferred." (PMID 41035732, 2025). "Our study found that oxidative stress, Wnt/β-catenin and Hedgehog/Gli1 signalings were involved in p,p′-DDE-induced colorectal adenocarcinoma cell proliferation." (PMID 25386960, 2014).
demyelination (2 papers, 2021 to 2025). "For example, the loss of Gli1 leads to a transient increase in the proliferation of neural stem cells in the subventricular zone during the early stage of demyelination-induced disease." (PMID 41208887, 2025). "On the other hand, the pathway regulates NPC proliferation in the SVZ from healthy adult mice, whereas blockade of Gli1 is necessary to recruit a subset of NPCs that exclusively differentiate into oligodendroglial cells in mouse models of CNS demyelination." (PMID 35082605, 2021). "Like the pharmacological blockade of Gli1, its genetic inhibition was found to be crucial to improve the functional outcome of animals in a relapsing/remitting EAE model and to promote remyelination in the cuprizone model of CNS demyelination." (PMID 35082605, 2021).
emphysema (2 papers, 2019 to 2024). "Indeed, previous studies showed that lung cells from human COPD/emphysema patients exhibited Hh hyperactivation with upregulated GLI1 and PTCH1, compared with those from non-COPD/emphysema controls." (PMID 31323955, 2019).
epilepsy (2 papers, 2013 to 2015). A brain disorder characterized by episodes of abnormally increased neuronal discharge resulting in transient episodes of sensory or motor neurological dysfunction, or psychic dysfunction. "To study the proliferative activity of a cohort of Gli1-expressing granule cell progenitors in epilepsy, we treated double-transgenic Gli1-CreERT2::Brainbow reporter mice with tamoxifen at postnatal week 7 to trace the lineage of these cells." (PMID 26756038, 2015). "Here, we used a conditional Brainbow reporter line driven by an inducible Gli1-CreERT2 promotor construct to trace the lineage of clones arising from Gli1-expressing granule cell progenitors in the pilocarpine model of epilepsy." (PMID 26756038, 2015).
epithelioid sarcoma (2 papers, 2025). An aggressive malignant neoplasm of uncertain differentiation, characterized by the presence of epithelioid cells forming nodular patterns. "For instance, alveolar soft part sarcoma, GLI1-altered ST tumor, and epithelioid sarcoma, jointly comprising 1.5% (2 of 128) of OSTJS in our series, overtly favor the tongue compared to other intraoral anatomic sites." (PMID 40526340, 2025).
gastritis (2 papers, 2013 to 2023). Inflammation of the stomach. "Relevant studies have shown that GLI1-activated transcription promotes the development of inflammatory diseases such as gastritis, and antagonizing GLI1 transcription can alleviate the inflammatory degradation of articular cartilage." (PMID 37929702, 2023). "Despite the absence of metaplasia, there were similar amounts of F4/80+ myeloid cells infiltrating the infected WT, Gli1+/− and Gli1−/− stomachs, demonstrating that Gli1 deletion prevented the transition from gastritis to SPEM." (PMID 23520544, 2013).